NES (nestin)
Diseases named in the same sentence as NES in open-access papers (continued):
Sharing a sentence is not in itself a finding about the gene and the disease.
ischemia (26 papers, 2007 to 2025). A hypoperfusion of the BLOOD through an organ or tissue caused by a PATHOLOGIC CONSTRICTION or obstruction of its BLOOD VESSELS, or an absence of BLOOD CIRCULATION. "Taken together, these findings suggest that locally activated nestin+ iNSPCs generate DCX+ cells following ischemia, in accord with previous studies." (PMID 38534363, 2024). "The authors reported that nestin can be expressed in mature astrocytes or in brain microglia during ischemia or after treatment with lipopolysaccharide (LPS), thereby favoring differentiation toward gliosis." (PMID 37631975, 2023). "MG132 administered prior to preconditioning sessions restored numbers of nestin positive cells to the levels equivalent to those in untreated ischemia." (PMID 35250819, 2022). "Nestin expression in the M2-sEV group increased during the first 7 days after ischemia and then decreased." (PMID 33391532, 2021). "At the same time, we investigated the spatial and temporal evolution of NSCs and neuroblasts following ischemia by analyzing the expression of Nestin and Dcx from day 1 to day 7 after MCAO." (PMID 30131677, 2018). "On the 7th day after ischemia induction, nestin-positive cells were detected in the SVZ and the cortical peri-infarct area of PGZ rats; the cells seemed to migrate from the SVZ to the peri-infarct region." (PMID 29110250, 2018). "We evaluated neurological deficit score, brain infarct volumes, along with the immunohistochemical staining of nestin and caspase-3 in the sub-granular zone of the injured hemisphere on the 1st, 3rd, 7th, and 14th day after the onset of ischemia." (PMID 29312600, 2017). "In the ischemic core area, the induction of nestin expression occurs 3 days after ischemia and continues for at least 28 days after ischemia; however, the cellular construction of nestin positive cells changes during this period." (PMID 28913350, 2017). "Based on the results obtained by in vivo imaging, i.e., peak signal induction of nestin, the ischemic brains were collected at 3–7 days after ischemia and stained for nestin and GFP." (PMID 28253906, 2017). "We evaluated neurological outcomes, infarct volume, and the expression of nestin and caspase-3 in the sub-granular zone on the 1st, 3rd, 7th, and 14th day after the onset of ischemia." (PMID 29312600, 2017). "A few previous studies have demonstrated correlations between nestin and both infarct size and neurological deficit score on the 3rd, 7th or 14th day after the onset of ischemia in focal cerebral ischemia and/or reperfusion injury." (PMID 29312600, 2017). "Compared to the normothermic group, MH significantly increased the number of nestin+ cells and reduced the number of caspase-3+ cells at all time points after the onset of ischemia (***p < 0.05)." (PMID 29312600, 2017). "Saino’s report demonstrated that inhibiting endogenous Tregs reduced Nestin+ cells after ischemia, suggesting that Tregs play a role on maintaining and promoting neurogenesis during ischemic brain injury." (PMID 26441532, 2015). "The results indicatedthat the treatment group had more nestin expressioncompared with the ischemia group in both theDG and SVZ areas." (PMID 24611146, 2014). "The transient upregulation of GAP43 apparently represents a transition event during the acquisition of a neuronal-like phenotype and a type I diabetic environment attenuated the neurogenic response of cardiac nestin(+) cells to ischemia and 6-hydroxydopamine." (PMID 23938193, 2013). "It was suggested that increased co-expression of GFAP and Nestin in the cortex following focal ischemia might indicate reversion to an immature cell state, potentially reflecting astrocyte reprogramming towards neuronal differentiation." (PMID 39851520, 2025). "In addition, HBO-PC normalized the number of nestin positive cells to the level found in the sham group, thus preventing nestin depletion after untreated ischemia." (PMID 35250819, 2022).
ischemia (continued). "As a result of ischemia, astrocytes release vimentin, nestin, IL-1β, monocyte chemotactic protein-1, and glial fibrillary acidic protein, which contribute to the development of reactive gliosis and the formation of glial scars after ischemia." (PMID 33922467, 2021). "Interestingly, we found that MH significantly increased the number of nestin+ cells in the sub-granular zone of the injured hemisphere at all time points after the onset of ischemia in rats with MCAO/R." (PMID 29312600, 2017). "The present study has reaffirmed and further expanded on the latter paradigm as the superimposition or the pre-existence of a type I diabetic environment abrogated the neurogenic response of cardiac resident nestin(+) cells to ischemia and 6-hydroxydopamine, respectively." (PMID 23938193, 2013). "Signs of glial activation in transgenic retinas became more manifest with time: elevated expression of GFAP in the inner parts of the retina and of nestin on P30 indicates the presence of either ischemia and/or mechanical forces exerting traction on the retina." (PMID 22880002, 2012). "Surprisingly, we found that the number of nestin+ cells in the sub-granular zone of the injured hemisphere correlated well with neurological deficit score in the normothermic rats but with infarct volume in the hypothermic rats when data from the 1st day after the onset of ischemia was excluded." (PMID 29312600, 2017). "Furthermore, rodents in the IA treatment group showed less neurologic impairment and a corresponding increase in the number of Brdu/nestin and Brdu/NeuN double positive neurons in the parenchymal ischemia tissue following middle cerebral artery occlusion compared to matched controls." (PMID 27057202, 2016). "The present study measured the BrdU+/Nestin+ cells and BrdU+/DCX+ cells related to ET-1-induced ischemia in the SVZ and found that the proliferation of NPCs can be enhanced by LCN DBS combined with pasta reaching training, initiated at week 2 poststroke." (PMID 33024145, 2020). "The up-regulation of nestin and GFAP in Müller glia cells indicated that the transgenic retina experienced a gliotic response that is likely to be triggered by ischemia due to the missing retinal vasculature." (PMID 22880002, 2012). "We used nestin–green fluorescent protein (GFP) transgenic reporter mouse line, in which neural stem/progenitor cells are easily visualized and quantified by the expression of GFP, to determine the alterations in the dentate gyrus (DG) after focal ischemia in the prefrontal cortex." (PMID 33015039, 2020). "We assessed neurological outcomes, infarct volume, and the expression of nestin and caspase-3 in the hippocampal dentate gyrus following middle cerebral artery occlusion (MCAO) followed by reperfusion, with mild hypothermia (MH) treatment at the onset of ischemia in a MCAO rat model." (PMID 29312600, 2017). "The number of nestin+ cells correlated with neurological deficit score in the normothermic group, and with infarct volume in the hypothermia group except for the first day after the onset of ischemia." (PMID 29312600, 2017). "These ischemia/injury-induced multipotent stem cells (iSCs) expressed not only pericytic markers (e.g., PDGFRβ, neural/glial antigen 2 (NG2), and alpha-smooth muscle actin (αSMA)), but also various stem cell markers (e.g., nestin, c-myc, Klf4, and Sox2)." (PMID 32887241, 2020).
lung carcinoma (26 papers, 2012 to 2025). "Despite the importance of the lung (for example, lung cancer is the leading cause of cancer-related deaths worldwide) and nestin in current medicine, there is relatively little information about their interaction." (PMID 34943921, 2021). "Regarding to focus at the association of nestin with lung cancer staging, we have done some analysis on the relationship between nestin and T staging or N staging." (PMID 26015397, 2015). "We show that pharmacological blockade of BMP type I receptors causes significant growth inhibition of lung cancer cells expressing Oct4 or nestin." (PMID 24160469, 2013). "Notably, studies relating to lung cancer (three qualifying articles) showed a significant association between nestin and lung cancer stage (OR = 2.00, 95% CI = 1.16–3.44)." (PMID 26015397, 2015). "To assess whether nestin plays a role in lung cancer cell proliferation, we stably transfected A549 and H460 cells with plasmids encoding shRNAs targeting the nestin transcript or with scrambled shRNA control plasmids, and measured changes in proliferation-related attributes." (PMID 24498263, 2014). "At the protein level, brain metastases from lung cancer show expression of the neural/glial marker Nestin." (PMID 37046805, 2023). "During this process, cells lose their cell-cell contact and acquire a mesenchymal phenotype, driven by the expression of some mesenchymal markers, such as Nestin and Vimentin in lung cancer." (PMID 37046805, 2023). "For this purpose, we chose several common markers associated with lung cancer CSCs: aldehyde dehydrogenase (ALDH), CD44, Octamer-binding transcription factor 4 (Oct4), KIT proto-oncogene, receptor tyrosine kinase (c-Kit), and Nestin." (PMID 37233697, 2023). "The expression of nestin was studied in 21 lung cancer cell lines by Western blot and was detected immunohistochemically in surgically resected SCLC primary tumors (two samples) and metastatic SCLC tumors obtained from autopsies (two samples)." (PMID 34943921, 2021). "Most of the papers reviewed in the previous section presented evidence of an important role of nestin in the presentation and progression of lung cancer." (PMID 34943921, 2021). "The expression and function of nestin have also been analyzed in other subtypes of lung cancer, such as small cell lung cancer (SCLC)." (PMID 34943921, 2021). "On the other hand, several of the articles reviewed in the previous section presented evidence of a role of nestin in the ability of lung cancer to metastasize to other organs." (PMID 34943921, 2021). "In lung cancer, Nestin was reportedly capable of protecting Nrf2 from kelch-like ECH-associated protein 1 (Keap1)-modulated degradation and was able to increase the expression levels of antioxidant enzymes." (PMID 34837964, 2021). "Nestin binds directly with both Keap1 and Nrf2 and upregulates Nrf2 expression to modulate oxidative equilibrium in lung cancer." (PMID 34772403, 2021). "More research is necessary to establish the true value of nestin expression as a prognostic factor and therapeutic target in lung cancer in addition to its usefulness in therapeutic approaches for pulmonary diseases." (PMID 34943921, 2021). "Immunohistochemical analysis of specimens from NSCLC patients also supported the presence of Nestin in the nuclei of lung cancer cells." (PMID 30190500, 2018). "To test this possibility, we first overexpressed and immunoprecipitated Flag-Nestin in lung cancer cells." (PMID 30190500, 2018). "To determine the underlying mechanism, we first observed the subcellular localization of Nestin in vitro, and found that Nestin was present in the nuclei of the tested lung cancer cell lines." (PMID 30190500, 2018). "To identify the mechanistic contributions of Nestin to tumor pathogenesis, we used short hairpin RNAs (shRNAs) to deplete Nestin in the lung cancer cell lines, A549 and H1299." (PMID 30190500, 2018).
lung carcinoma (continued). "For the analysis stratified by cancer category, three articles that included 87 cases and 207 controls were used to evaluate the relationship between nestin and lung cancer (median or advanced stage vs. early stage)." (PMID 26015397, 2015). "In human lung cancer xenograft models, primary tumor growth rates and lung metastasis were analyzed using consecutive tumor volume measurements and nestin immunoreactivity in nude mouse lungs." (PMID 26258071, 2015). "Further investigations of nestin and lung cancer stage on a larger scale are needed to verify this result and firmly establish nestin as a cancer malignancy biomarker." (PMID 26015397, 2015). "Previous reports of pancreatic, prostate, and lung cancers revealed that nestin expression was important for migration and invasion capabilities of tumor cells, which subsequently resulted in poor prognoses." (PMID 24785714, 2014). "By extension, these data imply that elevated nestin levels in lung cancer cells stimulate proliferation and metastasis by increasing the activity of this pathway." (PMID 24498263, 2014). "CD133+ and CD44+ cells are reported to represent “cancer stem cells” in lung carcinomas, which have also been shown to express Oct4 and/or nestin." (PMID 24160469, 2013). "Our studies suggest that lung cancer cells expressing Oct4 or nestin are different cell populations." (PMID 24160469, 2013). "We provide evidence that lung cancer cells expressing Oct4 or nestin are different cell populations." (PMID 24160469, 2013). "Immunofluorescent imaging of lung cancer cell lines showed that nestin is expressed in the cytoplasm filaments." (PMID 24160469, 2013). "We further delineate the heterogeneity of lung cancer by showing that Oct4, nestin, and Neun are expressed in lung cancer cell lines and primary lung tumors." (PMID 24160469, 2013). "Western blot analysis for nestin showed strong expression in all the lung cancer cell lines examined." (PMID 24160469, 2013). "Lung cancer cells expressing Oct4 or nestin were isolated from lung cancer cell lines by stably transfecting the Oct4 promoter or nestin promoter expression vectors that induce expression of the green fluorescent protein reporter." (PMID 24160469, 2013). "M5 expressed pericyte-associated genes (RGS5, PDGFRB, NES, THY1, KCNJ8) and showed strong similarity to curated pericyte signatures, including pan-cancer C8_RGS5 pericytes, healthy human prostate pericytes and pericytes from lung cancer." (PMID 41378308, 2025). "This antiapoptotic role of nestin has been reported in lung-cancer-related studies." (PMID 34943921, 2021). "Several meta-analyses have examined the effect of nestin expression on lung cancer." (PMID 34943921, 2021). "However, although nestin is known to have a role in various malignancies, there is relatively little information in the literature about the effect of nestin expression in lung cancer." (PMID 34943921, 2021). "According to most of the reports in the literature, nestin expression in lung cancer leads to an aggressive phenotype and resistance to chemotherapy as well as radiation treatments due to the upregulation of phenomena such as cell proliferation, angiogenesis, and metastasis." (PMID 34943921, 2021). "We also analyzed nestin expression in three drug-resistant lung cancer cell lines." (PMID 32903755, 2020). "The results fully showed that high levels of Nestin expression was closely correlated with poor survival and could be used as a prognostic biomarker for patients with lung cancer." (PMID 31695040, 2019). "In addition, we analyzed the overall survival (OS) and disease free survival (DFS) in the two lung cancer patients groups of 15% cutoff high and 15% cutoff low Nestin expression, which was based on The Cancer Genome Atlas (TCGA) databases." (PMID 31695040, 2019).
lung carcinoma (continued). "Notably, we demonstrate that there is a positive-feedback loop between Nestin and Nrf2, and that it is responsible for mediating the antioxidant responses and maintaining cellular redox homeostasis in lung cancer." (PMID 31695040, 2019). "Our previous results also revealed Nestin expression in the nuclei of lung carcinoma cells." (PMID 30190500, 2018). "In summary, our meta-analysis provides evidence of an association between positive/high nestin and cancer stage, suggesting that knowledge of nestin expression status could facilitate cancer staging, especially in lung cancer." (PMID 26015397, 2015). "Quantitation of nestin immunoreactivity revealed ~10-fold increase in lung metastasis from HABP2 overexpressing primary tumors indicating the importance of this molecule in lung cancer progression." (PMID 26258071, 2015). "Downregulation of nestin efficiently inhibited lung cancer cell proliferation, which might be through affecting cell cycle arrest and Akt-GSK3β-Rb signaling pathway." (PMID 24498263, 2014). "We previously demonstrated that the majority of tumor cells in non-small cell lung cancer samples are nestin-positive and showed that nestin expression was positively correlated with the subset of lung cancer patients displaying poor outcomes and high levels of proliferative markers." (PMID 24966803, 2014). "Our data collectively suggest that tumor cells expressing nestin promote proliferation in NSCLC, which may constitute a key mechanism of nestin-mediated malignancy in lung cancer cells." (PMID 24498263, 2014). "Nestin is associated with neoplastic transformation, but the mechanisms by which nestin contributes to invasion and malignancy of lung cancer remain unknown." (PMID 24498263, 2014). "Thus, the phenomena that nestin-expressing tumor cells are important for proliferation, migration, and metastasis in lung cancer." (PMID 24498263, 2014). "While our results indicate that nestin acts through the Akt-GSK3β-Rb signaling pathway to contribute to proliferation in lung cancer cells, other aspects of tumor malignancy, such as angiogenesis, lymphangiogenesis and tumor metabolism, are yet to be directly examined." (PMID 24498263, 2014). "Targeted regulation of nestin may thus have therapeutic applications in human lung cancer treatment." (PMID 24498263, 2014). "Our findings provide preliminary evidence for a role of nestin in lung cancer cell proliferation." (PMID 24498263, 2014). "To access whether the heterogeneity identified in the lung cancer cell lines occurs in primary lung cancer, we examine by immunohistochemistry (IHC) the expression of Oct4A, Nestin, and NeuN in NSCLC." (PMID 24160469, 2013). "It is not known whether the BMP signaling cascade regulates growth and the expression of Id proteins of lung cancer cells expressing the stem cell markers Oct4 and/or nestin." (PMID 24160469, 2013). "By quantitative RT-PCR, nestin was expressed in all 6 lung cancer cell lines examined." (PMID 24160469, 2013). "Since nestin is a marker of neural cells types, we examined whether lung cancer cells express NeuN (Neuronal Nuclei)." (PMID 24160469, 2013). "We isolated from lung cancer cell lines, cells that express Oct4 or nestin." (PMID 24160469, 2013). "Notwithstanding the multiple systematic meta-analysis that addressed the impact of Sox2, nestin, and vimentin as independent predictors in human lung cancer prognosis, two reports demonstrated the clinicopathological and prognostic significance of the nucleolin expression in lung cancer patients." (PMID 35565346, 2022). "Additionally, they analyzed nestin expression in drug-resistant lung cancer cell lines." (PMID 34943921, 2021). "Given the previous study results indicating that Nestin and Nrf2 play essential roles in tumor phenotype and cellular redox homeostasis of lung cancer, we hypothesized that Nrf2 is also involved in the Nestin-modulated GC cell viability, apoptosis, antioxidant gene expression, and metastasis." (PMID 34772403, 2021).